EGFR (epidermal growth factor receptor)
Diseases named in the same sentence as EGFR in open-access papers (continued):
Sharing a sentence is not in itself a finding about the gene and the disease.
adenocarcinoma (continued). "All patients were adenocarcinoma and unknown EGFR mutation status." (PMID 29435131, 2018). "Among stage IV patients, increased age, Medicaid/no/unknown insurance status, death within 2 months of diagnosis and comorbidity were inversely associated with EGFR testing; erlotinib treatment was less likely among smokers and patients with non-adenocarcinomas." (PMID 27294665, 2016). "Current guidelines recommend testing all patients with metastatic NSCLC adenocarcinomas for the presence of activating EGFR mutations; in addition, these guidelines suggest the use of EGFR-TKIs as first-line therapy in patients with adenocarcinoma and a known EGFR mutation." (PMID 26622815, 2015). "Pan-HDAC inhibitors such as PS may provide a viable option to (re) sensitize NSCLC cells, particularly of adenocarcinoma subtype with EGFR mutations, to the antiproliferative effects of the TKI erlotinib, warranting further development of this approach within a clinical phase II trial." (PMID 26675484, 2015). "Moreover, n-Dodecane analysis from adenocarcinoma patients might be useful to discriminate the EGFR mutation." (PMID 25490772, 2014). "Therefore, these factors (female gender, adenocarcinoma, distant metastasis and chemotherapy) may increase the probability of EGFR gene mutations." (PMID 25013503, 2014). "However, most of our patients were male, smokers and non-adenocarcinomas, which might be the main reason for the lower incidence of the activated EGFR mutation." (PMID 24205040, 2013). "Notably, the presence of ALK fusions was associated with histological adenocarcinomas and with wild-type EGFR and KRAS status, which may be of clinical relevance in targeted therapy using ALK inhibitors." (PMID 20624322, 2010). "Table II may be of assistance in respect of KRAS and EGFR mutational status in adenocarcinoma." (PMID 19672420, 2009). "We found that BAC component positively related to EGFR mutations, solid component inversely related to EGFR gene mutations, and that well-to-moderately differentiated adenocarcinomas had higher incidence of EGFR gene mutations than poorly differentiated adenocarcinomas." (PMID 16052218, 2005). "In this cohort, 29.41% (n = 20) of adenocarcinoma cases tested positive for a targetable mutation as follows: 85% (n = 17) were KRAS G12C, and 15% (n = 3) were the EGFR E19del." (PMID 41658662, 2026). "A biopsy of the lung mass confirmed invasive, moderately differentiated adenocarcinoma, with immunohistochemical markers (TTF1 + ) and an epidermal growth factor receptor (EGFR) mutation (L858R), indicating a bronchopulmonary origin." (PMID 41502993, 2025). "First, resensitization to EGFR TKI from existing adenocarcinoma clones that persist after histologic transformation." (PMID 41256964, 2025). "In EGFR-mutant NSCLC, particularly adenocarcinomas, low IL-1β expression was associated with significantly improved OS." (PMID 40940992, 2025). "SCLC cells originating from EGFR-mutant adenocarcinomas undergo a transition that leads to the cessation of EGFR expression, hence conferring resistance to EGFR inhibitors." (PMID 41013839, 2025). "A total of 1663 EGFR-mutated NSCLC cases, including 1454 adenocarcinoma and 33 squamous histology, were analyzed." (PMID 40940992, 2025). "The most common driver mutations are EGFR (present in 45% of Asian and 20% of Caucasian adenocarcinoma patients) and KRAS (found in 25% of adenocarcinomas)." (PMID 39852181, 2025). "The cohort analyzed here consisted mainly of elderly patients with adenocarcinoma, a typical population group for EGFR-mutant NSCLC." (PMID 40768678, 2025). "For instance, EGFR-mutant adenocarcinomas exhibit elevated Tregs and low effector T cell infiltration, while SCCs display robust but suppressed immune infiltrates due to extensive immune checkpoint upregulation." (PMID 40342732, 2025). "Of the 49 patients randomized, 80% had adenocarcinoma, 84% were EGFR or ALK wild-type, and 94% had synchronous metastases." (PMID 40805152, 2025).
adenocarcinoma (continued). "To elucidate the mechanisms underpinning SCLC transformation, we examined the transcriptomics of EGFR-mutant and transformed adenocarcinomas (T-LUAD)." (PMID 40437627, 2025). "clinical prioritization of detecting actionable driver mutations (e.g., EGFR, ALK) for guiding first-line therapy, particularly in adenocarcinoma; c." (PMID 41002559, 2025). "A 67-year-old woman with EGFR exon 19–deleted adenocarcinoma received afatinib followed by long-term osimertinib." (PMID 41446706, 2025). "In contrast, due to frequently associated genetic mutations like epidermal growth factor receptor (EGFR) mutation, adenocarcinoma patients have a better treatment response and improved progression-free survival rates." (PMID 40566615, 2025). "EGFR mutations were most common (35.9%), followed by ALK rearrangements (14.2%), especially in adenocarcinoma group (p < 0.001)." (PMID 41002559, 2025). "Patients included in the training cohort were younger with a higher proportion of females and patients diagnosed with adenocarcinoma, which were consistent with classic clinical features of patients with EGFR-mutant NSCLC." (PMID 40831747, 2025). "In studies by Ferre and Marcoux, median times from initiation of treatment to phenotypic transformation for EGFR-mutant adenocarcinomas were 16 and 17.8 months, respectively." (PMID 40040728, 2025). "Epidermal growth factor receptor (EGFR) gene mutations are prevalent driver mutations in NSCLC, particularly adenocarcinomas." (PMID 40701777, 2025). "Within adenocarcinoma, exploratory molecular subgroups showed: EGFR 10/18 (55.6%) brain; KRAS 4/9 (44.4%) liver; ALK 3/3 (100%) bone." (PMID 41294679, 2025). "Conversely, in its sole error in the assessed queries, the PDF+Prompt model recommended only Amivantamab for treatment of an EGFR exon 20 insertion adenocarcinoma, while neglecting to include carboplatin or pemetrexed." (PMID 40271313, 2025). "Patients with EGFRmut adenocarcinoma were divided into two groups depending on response after two months of EGFR TKI therapy: the disease progression group and the disease control group." (PMID 39852160, 2025). "A biopsy performed on the left adrenal mass confirmed the diagnosis of adenocarcinoma recurrence, and PCR analysis conducted on the biopsy specimen indicated the presence of an EGFR exon 19 deletion." (PMID 40422529, 2025). "Epidermal growth factor receptor (EGFR) mutations and anaplastic lymphoma kinase (ALK) fusions were found to be specific to TRU-type adenocarcinomas." (PMID 38710944, 2025). "In adenocarcinoma, tyrosine kinase inhibitors were developed for EGFR mutations and ALK and ROS1 translocations and were approved for use in the treatment of advanced stage adenocarcinomas." (PMID 40076671, 2025). "Approximately 30% to 40% of patients in Asia have epidermal growth factor receptor (EGFR) mutated-positive NSCLC, and it can be up to 64.5% in the case of adenocarcinoma." (PMID 40978050, 2025). "The consistent result was seen with younger age, female sex, adenocarcinoma, p-stage II, positive EGFR/ALK, and ICI by multivariate analysis." (PMID 40676423, 2025).
adenocarcinoma (continued). "Histologically, EGFR-mutant adenocarcinomas initially characterized by glandular differentiation and positive expression of markers such as TTF-1 and Napsin A undergo a pronounced shift upon transformation." (PMID 41516316, 2025). "In adenocarcinoma subgroups, EGFR-mutant tumors most often metastasized to the brain (55.6%), KRAS-mutant tumors to the liver (44.4%), and ALK-rearranged tumors to bone (100%)." (PMID 41294679, 2025). "Estas mutaciones somáticas, que producen la activación constitutiva de la quinasa de EGFR, son más frecuentes en mujeres, en los pacientes con adenocarcinoma, de raza asiática, y en aquellos que nunca han tenido hábito tabáquico." (PMID 40977824, 2025). "EGFR protein overexpression was also significantly more commonly observed in adenocarcinomas with EGFR amplification." (PMID 40310364, 2025). "EGFR mutations, which occur in approximately 32% of NSCLC cases worldwide, are particularly common in the adenocarcinoma subtype." (PMID 38893104, 2024). "The frequency of common EGFR mutations, specifically Exon 19 deletion and Exon 21 L858R, is high in patients with NSCLC, predominantly adenocarcinoma, particularly in individuals younger than 50 years, male smokers, and female non-smokers." (PMID 39429333, 2024). "She underwent a supraclavicular lymph node biopsy that showed adenocarcinoma of pulmonary origin, epidermal growth factor receptor (EGFR) positive." (PMID 39811212, 2024). "An in vitro study revealed that EGFR mutant cells were less sensitive to fluorouracil than were EGFR wild-type cells High expression of DPD, a 5-fluorouracil degrading enzyme, correlated with EGFR mutation in adenocarcinoma cells and tissues." (PMID 39255996, 2024). "In the Osimertinib-resistant cohort, an 82-year-old female was originally diagnosed with an adenocarcinoma harboring EGFR exon 19 deletion." (PMID 39456595, 2024). "This real‐world study aimed to compare the effectiveness and safety of first‐line bevacizumab and ramucirumab in patients of advanced EGFR‐mutant adenocarcinoma receiving a first‐line EGFR TKI." (PMID 38523603, 2024). "Guidelines recommend testing for driver mutations (e.g., EGFR, ALK, ROS1) in advanced NSCLC, particularly adenocarcinoma." (PMID 39429333, 2024). "In our sample group, we identified only one patient with an EGFR mutation and one with a KRAS mutation (both patients have adenocarcinoma)." (PMID 38893104, 2024). "In previous studies, combined SCLC (combined with adenocarcinoma component) were predominated in SCLC which harbored EGFR mutations, while EGFR mutations were more common in pure SCLC in the present study." (PMID 37436674, 2024). "In adenocarcinomas cohort, EGFR was the primarily altered gene for both LUAD and MIA with a frequency of 62% and 56%, respectively." (PMID 38112031, 2024). "Several biomarker-guided therapies have been approved, targeting genes frequently altered in adenocarcinoma, such as EGFR, BRAF, MET, ALK, ROS1, RET and NTRK." (PMID 39199558, 2024). "Adenocarcinoma was the predominant histological type (71.3%), and most patients had a wild-type epidermal growth factor receptor (61.1%)." (PMID 39350284, 2024). "Regarding adenocarcinoma, the patient was initiated on EGFR tyrosine kinase inhibitors, which resulted in a significant regression of the lung mass." (PMID 39811212, 2024). "Epidermal growth factor receptor (EGFR) gene mutations are prevalent driver mutations in non-small cell lung cancer (NSCLC), particularly adenocarcinomas." (PMID 39497876, 2024).
adenocarcinoma (continued). "Significant differences can be found in the mutation rate of EGFR (60.9% vs 11.9%), KRAS (12.2% vs 25.0%), STK11 (1.5% vs 11.9%), FGFR3 (2.4% vs 0.0%) and ERBB4 (1.2% vs 6.1%) between adenocarcinoma in our cohort and TCGA-LUAD data (all p < 0.001)." (PMID 38496837, 2024). "Our study suggests a need for further research to explore the molecular mechanisms behind the differential response of ASC and pure adenocarcinomas to EGFR-TKI therapy." (PMID 39026979, 2024). "Comparison of clinical features and metabolic parameters between EGFR wild-type and mutant-type patients with adenocarcinoma." (PMID 38250731, 2024). "Current treatment guidelines and clinical trials predominantly focus on adenocarcinoma, leaving a gap in tailored therapeutic strategies for ASC patients with EGFR mutations." (PMID 39026979, 2024). "EGFR mutations, ALK, and ROS1 translocations were identified almost exclusively in patients with adenocarcinoma in line with reported scientific literature." (PMID 39512773, 2024). "To further analyse the induction of PRMT5 expression by STAT3 in NSCLC cells, we generated STAT3-knockout (STAT3-KO) cells by using the CRISPR/Cas9 system in A549 (EGFR wild type, adenocarcinoma) and HCC827 cells (EGFR mutant, adenocarcinoma)." (PMID 38760429, 2024). "EGFRmut HCC827G/G, H1975G/G and EGFRwt H460G/G, A549G/G, H1299C/C and H1437C/C cells were selected for further experiments based on their common histology (adenocarcinoma) and their different status of EGFR and rs822336." (PMID 38528526, 2024). "This argument is enhanced by previous reports showing that in adenocarcinoma cells of the lung, the identified Src kinase responsible for EGFR transactivation was Lyn." (PMID 38145300, 2024). "The percentage of patients with a high CYFRA21‐1:CEA ratio was also significantly higher in the ALK group (28%) compared with the EGFR group (14%) in cases restricted to adenocarcinoma (p = 0.004)." (PMID 38400801, 2024). "Some of the identified mutations include epidermal growth factor receptor (EGFR), where mutations occur in 15% of NSCLC adenocarcinoma cases." (PMID 38893088, 2024). "Our study shows that lung ASC with EGFR mutations respond effectively to EGFR-TKI treatment, albeit with a slightly lower efficacy compared to pure adenocarcinomas." (PMID 39026979, 2024). "The KRAS and EGFR pathways in adenocarcinoma are mutually exclusive, which suggests different molecular pathways being implicated in the development of adenocarcinoma between smokers and non-smokers." (PMID 36661704, 2023). "The most prevalent molecular subtype in NSCLC is EGFR-mutant, with a prevalence of 15–20% in adenocarcinomas of patients in Caucasian populations and up to 50% in Asian populations." (PMID 37895255, 2023). "Currently, there are few real-world studies examining the survival outcomes of patients receiving perioperative chemotherapy and EGFR–TKIs for resected EGFR-mutant stage III adenocarcinoma." (PMID 37697233, 2023). "In this work, we considered adenocarcinoma only, and we focused on the classification of KRAS and EGFR mutations." (PMID 37508774, 2023). "Based on the literature review, the efficacy of EGFR-TKIs in lung SCC with EGFR mutant is lower than that in adenocarcinoma." (PMID 37781197, 2023). "Upon adagrasib resistance it was described histological transformation from adenocarcinoma to squamous a bit similar to what was seen in case of EGFR inhibitor resistance." (PMID 38239281, 2023). "Epidermal growth factor receptor (EGFR) mutations are found in up to 10% of Caucasians, and more than 40% of East Asian adenocarcinoma patients." (PMID 36617560, 2023). "This case series describes two patients diagnosed with stage IV adenocarcinoma with coexisting EGFR and ALK rearrangements." (PMID 38046784, 2023). "In some NSCLC patients, mainly adenocarcinoma, molecular alterations in driver genes, like EGFR, KRAS, HER2, ALK, MET, BRAF, RET,ROS1, and NTRK are recognized." (PMID 37346803, 2023).
adenocarcinoma (continued). "After receiving anti-programmed cell death protein 1/programmed death-ligand 1 (PD-1/PD-L1) treatment, adenocarcinoma patients positive for EGFR mutant show poorer responses than those with the wild-type." (PMID 37033978, 2023). "A 70-year-old, Vietnamese, male, smoker with 13 pack-years (py), in PS 1, was diagnosed with T3N2M1c NSCLC, adenocarcinoma type, harboring EGFR ex19del (p.E746_T751delinsVA)." (PMID 37685884, 2023). "EGFR‐TKIs has become an vital systemic treatment in patients with MPE‐NSCLC on account of adenocarcinoma as the predominant pathological type, which has a high rate of EGFR‐M, especially in the Asian population." (PMID 37288833, 2023). "In this study, the consistent rate of ctDNA EGFR detected by SuperARMS‐PCR in patients with non‐adenocarcinoma was higher than that in patients with adenocarcinoma." (PMID 36621813, 2023). "It is generally accepted that there are few effective chemotherapies for BM due to the blood–brain barrier, while EGFR-TKIs, especially osimertinib, can be used for BM of adenocarcinoma." (PMID 36750899, 2023). "Eighty-four patients with resected stage III EGFR-mutant adenocarcinoma were enrolled in this study." (PMID 37697233, 2023). "With respect to histology, 80/84 (95%) of the EGFR patients had adenocarcinoma, 3/84 were adenosquamous and 1/84 had a squamous subtype (this patient was a never-smoker)." (PMID 37622996, 2023). "This retrospective study aimed to compare the treatment outcomes, with a focus on OS, between patients with resected EGFR-mutant stage III adenocarcinoma who received either perioperative chemotherapy or EGFR-TKIs." (PMID 37697233, 2023). "In patients with adenocarcinoma, high PD-L1 expression was seen in 25 of 77 (32.5%) patients with EGFR wild-type tumors but only in 4 of 70 (5.7%) patients with EGFR-mutant tumors (P < 0.0001)." (PMID 37452277, 2023). "Few real-world studies have examined the survival outcomes of patients with resected EGFR-mutant stage III adenocarcinoma receiving perioperative chemotherapy and EGFR–TKIs." (PMID 37697233, 2023). "Most prevalent actionable mutations in adenocarcinoma include KRAS, EGFR, ALK, RET, ROS1, BRAF, HER2, MET." (PMID 37301854, 2023). "All 18 EGFR/ERBB2 ex20 ins/dup-positive cases were adenocarcinomas and most frequently had the acinar predominant growth pattern (64%, n = 11)." (PMID 37284196, 2023). "The majority of patients had stage IV adenocarcinoma (97.4%) and exhibited EGFR exon 19 deletions (43.3%) and exon 21 L858R substitutions (49.3%)." (PMID 36670497, 2023). "Both EGFR and KRAS mutations were detected in patients with a combined histology (SCLC plus adenocarcinoma)." (PMID 38203395, 2023). "Studies suggest that EGFR mutations are present in ≥40–68% of Thai NSCLC patients, with higher frequencies among those with adenocarcinoma histology." (PMID 36895484, 2023). "EGFR and ALK mutation testing is suggested for patients with NSCLC, adenocarcinoma, and large-cell carcinoma by the National Comprehensive Cancer Network Clinical Practice Guidelines in Oncology." (PMID 36290461, 2022). "A point in favour of this possibility is that almost all SCLCs that arose from EGFR-mutant adenocarcinoma retained the molecular signature, i.e., an EGFR activating mutation." (PMID 35456982, 2022). "In order to observe and quantify the progression of plasmonic fusion within a fully confluent, monolayered cell culture, adenocarcinoma MDA-MB-468 cells were incubated for 3 h in a medium containing 15 × 1010 EGFR-specific gold nanoparticles per ml." (PMID 35504928, 2022). "Starting from the results of a few murine models, the focus was mainly on alveolar type II cells that initially were supposed to potentially develop both SCLC and EGFR-mutant adenocarcinoma." (PMID 35456982, 2022). "Median PFS in adenocarcinoma patients treated with first- and second-generation of EGFR TKIs was 17 months." (PMID 35522668, 2022).